TRPA1 (transient receptor potential cation channel subfamily A member 1)
Diseases named in the same sentence as TRPA1 in open-access papers (continued):
Sharing a sentence is not in itself a finding about the gene and the disease.
pneumonia (1 paper, 2023). An acute, acute and chronic, or chronic inflammation focally or diffusely affecting the lung parenchyma, caused by an infection in one or both of the lungs (by bacteria, viruses, fungi, or mycoplasma.). "Consequently, TRPA1 has emerged as a key target for treating respiratory tract inflammation, particularly lung inflammation, making the search for novel TRPA1 channel modulators essential for the development of safe and effective drugs for pneumonia." (PMID 37446875, 2023).
prostate adenocarcinoma (1 paper, 2024). "TRPA1 is overexpressed in prostate adenocarcinoma without any relation to overall survival, cancer stage or metastasis." (PMID 39770499, 2024).
psychosomatic disorders (1 paper, 2025). "This review first outlines how epigenetic dysregulation contributes to psychosomatic disorders through altered expression of genes such as GRM2, TRPA1, SLC6A4, NR3C1, leptin, BDNF, NAT15, HDAC4, PRKCA, RTN1, PRKG1, and HDAC7." (PMID 41439979, 2025).
rectum carcinoma (1 paper, 2024). "TRPA1 expression is lower in gastrointestinal malignancies (colon and rectum carcinoma) than in non-tumoral tissues, and it does not correlate with overall survival or disease-free survival." (PMID 39770499, 2024).
sarcoma (1 paper, 2024). A usually aggressive malignant neoplasm of the soft tissue or bone. "The correlation of TRPA1 expression with disease-free survival (DFS) returns a significant value (Mantel–Cox test, p < 0.05) for KIRC and sarcoma (SARC)." (PMID 39770499, 2024).
schwannoma (1 paper, 2025). A benign, usually encapsulated slow growing tumor composed of Schwann cells. "Pre-treatment of cultured mouse neurons with CM from painful schwannoma cell lines enhanced their responsiveness to noxious TRPV1 and TRPA1 agonists." (PMID 40794298, 2025). "Furthermore, culturing mouse dorsal root ganglion neurons with CM derived from painful schwannomas led to the upregulated expression of known inflammatory pain-related genes and an increased responsiveness to noxious agonists (capsaicin and/or cinnamaldehyde) of TRPV1 and TRPA1 calcium channels." (PMID 40794298, 2025).
Sciatica (1 paper, 2025). Pain in the lower back and hip radiating in the distribution of the sciatic nerve. "Interestingly, ferulic acid, present in PN-G, has been earlier reported to be effective against sciatica by reducing inflammation and peripheral sensitization through targeting RhoA/p38 MAPK pathway-mediated expressions of TRPA1 and TRPV1." (PMID 40969950, 2025).
Shock (1 paper, 2021). The state in which profound and widespread reduction of effective tissue perfusion leads first to reversible, and then if prolonged, to irreversible cellular injury. "In severe forms of systemic inflammation (e.g., septic shock), which is often associated with hypothermia and by enhanced production of H2S, the interaction between TRPA1 and H2S can play a crucial role in the development of the response and, as perspective, may serve as a therapeutic target." (PMID 34681216, 2021).
small cell carcinoma (1 paper, 2023). A neuroendocrine carcinoma composed of small malignant cells which are often said to resemble "oat cells" under the microscope. "This is interesting because small cell carcinoma is a disease of smokers, and TRPA1 is a well-established target for irritant compounds in cigarette smoke." (PMID 37240443, 2023). "In four human small cell carcinoma cell lines (H69, H146, H187 and H510), high TRPA1 mRNA expression was demonstrated using RT-PCR." (PMID 37240443, 2023). "Therefore, it may be worth exploring if TRPA1 can be targeted by antagonists to halt (or at least slow) the progression of small cell carcinoma." (PMID 37240443, 2023).
squamous cell carcinoma (1 paper, 2023). A carcinoma arising from squamous epithelial cells. "In vitro, TRPA1 and/or TRPV1 activation has been shown to kill squamous cell carcinoma cells." (PMID 37240443, 2023).
steatosis (1 paper, 2026). Increased lipid within the cytoplasm of cells. "We conclude that Trpa1 is expressed in hepatocytes and liver macrophages; however, the chronic alcohol-induced steatosis and inflammatory infiltration develop through a TRPA1-independent mechanism." (PMID 41827854, 2026).
stomach adenocarcinoma (1 paper, 2022). "From the GeneMANIA analysis, we extracted the best correlation of TRPA1 expression with the gene encoding A-kinase anchor protein 5 (AKP5), which is a scaffolding protein of the cytoskeleton and has increased levels in stomach adenocarcinoma." (PMID 36012311, 2022).
synovitis (1 paper, 2021). Inflammation of a synovial membrane. "Our previous works revealed that transient receptor potential ankyrin 1 (TRPA1) ion channels mediate the amplification of KOA synovitis." (PMID 34876884, 2021). "In animal experiments, the topical application of SP-NEs gel paste can effectively reduce synovitis of KOA rats and downregulate the gene and protein expressions of IL-1β, IL-18, and TRPA1." (PMID 34876884, 2021). "Above all, we believe that the role of SP-NEs in alleviating synovitis of KOA is related to its intervention in AMPK-mTOR signaling and subsequent negative regulation of TRPA1." (PMID 34876884, 2021).
thyroid cancer (1 paper, 2024). "A similar result was obtained for thyroid cancer, where TRPA1 is highly expressed only in infiltrated B cells, CD4+ T cells and dendritic cells and is correlated with better overall survival." (PMID 39770499, 2024).
tongue cancer (1 paper, 2025). A malignant neoplasm affecting the tongue. "While we have previously reported increased expression of TRPV1 and TRPA1 in TGs of mice with tongue cancer, we find that TRPV4 was neither abundantly expressed in nerves innervating murine tongue cancer nor in the TGs of mice with tongue cancer." (PMID 40144515, 2025).
type 1 diabetes (1 paper, 2020). "In addition, a recent study revealed that mechanical itch was developed in streptozotocin induced diabetic mice by activation of TRPA1, thus providing an explanation for itch and hypoalgesia in type 1 diabetes." (PMID 32664385, 2020).
vitamin D deficiency (1 paper, 2019). A nutritional condition produced by a deficiency of VITAMIN D in the diet, insufficient production of vitamin D in the skin, inadequate absorption of vitamin D from the diet, or abnormal conversion of vitamin D to its bioactive metabolites. "In mice, vitamin D deficiency increases the production of ROS which activates TRPA1 and TRPV1." (PMID 31731694, 2019). "In animal neuropathic pain models, vitamin D deficiency increases the production of reactive oxygen species (ROS) which result in cold pain via the activation of transient receptor potential ankyrin 1 (TRPA1) and contribute to mechanical hyperalgesia via the enhancement of NMDA receptor activation." (PMID 31731694, 2019).
vulvovaginal candidiasis (1 paper, 2018). Infection of the vulva and vagina with a fungus of the genus CANDIDA. "Dectin-1 signaling may activate TRPA1, which could be the mechanism that causes the vulvovaginal candidiasis-induced itch." (PMID 30240621, 2018).
cancer (87 papers, 2008 to 2026). A tumor composed of atypical neoplastic, often pleomorphic cells that invade other tissues. "Experimental results have shown that treatment with TRPA1 antagonists can effectively manage neuropathic pain caused by chemotherapy and cancer pain." (PMID 39273183, 2024). "The Cancer Genome Atlas data report that a high expression of the TRPA1 gene is associated with improved survival in intrahepatic biliary duct and bladder as well as liver cancers." (PMID 38612571, 2024). "Nevertheless, cancer pain is associated with TRPA1 blockade by triterpenoids or riterpenoids (and channel activation by ROS, but the process takes place in nociceptors and not in tumoral cells." (PMID 37507867, 2023). "In different cancer types, TRPA1 was found to be associated with oxidative stress tolerance and inflammation." (PMID 36012311, 2022). "Another polyphenol, resveratrol, was found to activate another type of the TRP (ankyrin 1) channels (TRPA1) in cancer-associated fibroblasts." (PMID 35455407, 2022). "Taken together, these studies support that enhanced sensory neuron excitability via TrpA1 activation represents a candidate mechanism underlying the pathogenesis of pain hypersensitivity in response to potentially a broad number of anti-cancer drugs." (PMID 29084244, 2017). "Our data encourage the consideration of TRPA1, the mesenchymal FGFR2c variant, and its hub signaling molecule PKCε as new molecular targets for precision oncology approaches to this recalcitrant cancer, which we hope will benefit an ever-larger group of patients." (PMID 38339360, 2024). "Schwann cell TRPA1 has been similarly implicated in cancer-related pain by regulating, via a macrophage colony-stimulating factor (M-CSF), macrophage expansion and oxidative stress amplification, finally targeting neuronal TRPA1 to signal pain." (PMID 37892239, 2023). "Recent studies have underlined the role of TRPA1 in cancer pain." (PMID 37892239, 2023). "However, until now, few studies have reported the relationship of TRPA1 and cancer-associated fibroblasts in fibrosis, which remains a mystery for scientists to reveal." (PMID 36278189, 2022). "In this review, we will summarize the role of TRPV1 and TRPA1 in pain associated with cancer and discuss molecules that have been reported to modulate these channels, focusing particularly on the mechanisms of channel activation associated with molecules released in the tumor microenvironment." (PMID 35053150, 2021). "The relevance of TRPA1 in the tumorigenic process may be related to putative changes in the cell cycle progression, which is a hallmark of cancer." (PMID 33479347, 2021). "TRPV1 and TRPA1 could be involved in the development of cancer-associated pain, mediated by the acidic tumor environment." (PMID 35053150, 2021). "Previous studies have shown that TrpA1 channels can be activated via indirect mechanisms resulting from the change in inflammation, oxidative stress, and mitochondrial toxicity associated with chronic exposure to anti-cancer drugs." (PMID 29084244, 2017). "Corydalis alkaloids, aconitine derivatives, and curcumin all exhibit activity on TRPV1 and TRPA1 channels, which are critical mediators of thermal and mechanical hyperalgesia in cancer pain." (PMID 41531828, 2026). "Overall, our findings indicate that FGFR2c, TRPA1 and lipid raft components represent promising targets for the development of novel cancer type-specific therapeutic strategies." (PMID 41735269, 2026). "TRPA1 is up-regulated in many cancer cell types and is regarded as one of the primary cancer cell redox sensors, being sensitive to H2O2, 4-HNE, 4-oxo-nonenal, and 4-hydroxyhexena." (PMID 40813985, 2025). "Nanoparticles that inhibit TRPA1 show significant potential as cancer treatments, especially for cancers overexpressing TRPA1, thus providing a promising approach for overcoming existing chemotherapy resistance." (PMID 39273183, 2024).
cancer (continued). "The role of TRPA1 and TRPV1 in tumor genesis is often associated with their effect on cell cycle progression, which is a hallmark of malignant tumors." (PMID 38612571, 2024). "For instance, from the group of coumarins, natural compounds described previously as antitumoral compounds, the 3-phenyl-coumarins and resveratrol inhibited TRPA1 in a cancer cell line." (PMID 39770499, 2024). "In this analysis, we intend to offer some clues regarding the expression of TRPA1 in patients related to overall survival, cancer stage and metastasis, immune infiltration and correlation with genes essential in inflammation and oxidative stress." (PMID 39770499, 2024). "In contrast, other studies suggest that TRPA1 activation promotes cancer growth and metastasis via inducing neovascularization and promoting epithelial cell migration." (PMID 38612571, 2024). "The high expression of TRPA1 is correlated with a better prognosis for several cancer types and correlates with cancer stage and metastasis, while in others the TRPA1 is pro-oncogenic." (PMID 39770499, 2024). "TRPA1 is highly permeable to Ca2+, which in turn affects cancer cells’ growth and migration and inhibits apoptosis in cancer cells." (PMID 38612571, 2024). "We provide here the first evidence of functional TRPA1 expression in human and mouse OS and the potential ability of its activation to reduce cancer cell viability." (PMID 38612571, 2024). "Studies have shown that activation of TRPA1 can promote cancer cell growth, invasion, and metastasis, which makes TRPA1 an attractive target for therapeutic intervention." (PMID 38430394, 2024). "This decrease occurs because brain astrocytes release exosomal miRNA-142-3p, which then targets and reduces TRPA1 levels in the cancer cells." (PMID 39408656, 2024). "Other studies supported the same results and considered TRPA1 a protective predictor in these cancers." (PMID 39770499, 2024). "Nevertheless, the lysosomal expression of TRPA1 in cancer cells surely deserves future investigation." (PMID 37174661, 2023). "Second, TRPA1 drug blockade also reduced dacarbazine-induced nociception in a melanoma tumor-associated pain model, suggesting that this receptor may be a pharmacological agent for chemotherapy-induced pain syndrome in cancer patients receiving dacarbazine antitumor therapy." (PMID 37039840, 2023). "In agreement with the pro-survival role of Ca2+ spiking in cancer cells, extracellular Ca2+ entry via TRPA1 was required to promote cell survival in TRPA1-enriched cancer cells challenged with H2O2." (PMID 37174661, 2023). "A possible, so far missing from experimental evidence, link between TRPA1, ROS, and cell proliferation is feasible because the main endogenous activators for TRPA1 in cancer are the products of oxidative stress." (PMID 37507867, 2023). "TRPA1 has also been shown to accelerate metabolism in cancer cells that require high concentrations of reactive oxygen species to maintain their high proliferation rates." (PMID 37039840, 2023). "In a cancer pain model, the M-CSF/macrophages/Schwann cell TRPA1 pathway functions to maintain pain and target the deletion of TRPA1 to reduce pain." (PMID 36875034, 2023). "Different preclinical models have shown the involvement of transient receptor potential ankyrin 1 (TRPA1) channels in cancer pain and chemotherapy-induced neuropathic pain." (PMID 36098890, 2023). "In cancer, TRPA1 activation in prostate tumor endothelial cells acts as a modulator of angiogenesis, since its activation promotes neovascularization, endothelial cell migration, and tubulogenesis in vitro in models of human prostate cancer." (PMID 37892239, 2023). "Then, we briefly survey the contribution of TRPA1-mediated intracellular Ca2+ signals to cancer cell proliferation, migration, and angiogenesis." (PMID 37174661, 2023). "As we have discussed, TRPA1 and acrolein have been reported to be involved in smoking, inflammation, and cancer." (PMID 37511605, 2023).
cancer (continued). "Certainly, the validation of TRPA1 as a novel molecular target for anticancer strategies would benefit from a wider knowledge of the impact of TRPA1-mediated Ca2+ signals in a more extensive array of cancer types." (PMID 37174661, 2023). "Herein, we sought to describe the opposing effects of ROS-dependent TRPA1 activation on cancer cell fate and propose the pharmacological manipulation of TRPA1 as an alternative therapeutic strategy to enhance cancer cell sensitivity to oxidative stress." (PMID 37174661, 2023). "Recent work demonstrated that TRPA1 channel protein is up-regulated in several cancer types and that TRPA1-mediated Ca2+ signals can either engage an antiapoptotic pro-survival signaling pathway or to promote mitochondrial Ca2+ dysfunction and apoptosis." (PMID 37393347, 2023). "As a future perspective, the interaction between natural and synthetic stilbenoids and TRPA1 should be thoroughly investigated in oncological settings to develop novel adjuvant therapeutics targeting TRPA1-expressing cancers." (PMID 37631147, 2023). "TRPA1-dependent extracellular Ca2+ entry can support several cancer hallmarks, including hyperproliferation, survival against pro-apoptotic stimuli, and invasive behavior." (PMID 37174661, 2023). "TRPA1 has become a new target for the treatment of inflammatory pain, neuropathic pain, and cancer pain." (PMID 36875034, 2023). "More recently, TRPA1 expression has been confirmed in the central nervous system and in cancer cells." (PMID 37174661, 2023). "This is the first evidence that TRPA1 activation leads to mitochondrial Ca2+ uptake in cancer cells." (PMID 37393347, 2023). "Oxidative stress defense is particularly important for cancer cells to gain anchorage independence, and TRPA1 channels can be directly activated by oxidants/electrophiles through cysteine modification and have the highest oxidative sensitivity." (PMID 37039840, 2023). "It has been reported that TRPA1 is involved in the pathogenesis of cancer and other inflammatory diseases, possibly by regulating the metabolism of CD8+ T cells." (PMID 36875034, 2023). "In the present section, we will briefly survey the mechanisms whereby extracellular Ca2+ entry via TRPA1 channels promotes cancer cell proliferation, survival, migration, and angiogenesis." (PMID 37174661, 2023). "In this section, we will review the regulatory role of TRPA1 in fibrosis in myocardial diseases, synovial diseases, pulmonary diseases, cancer and other diseases." (PMID 36278189, 2022). "Increasing mitochondrial stress and mitochondrial dysfunction through activation of TRPA1 has been suggested to account for apoptosis induction of cancer cells." (PMID 35982414, 2022). "For example, TRPA1, TRPC1, TRPV4, TRPV5, and TRPV6 exhibited higher CNV amplification, while TRPV1, TRPV2, TRPV3, and TRPC3 exhibited frequent CNV loss in cancer." (PMID 35614079, 2022). "In cancer cells, the activation of TRPA1 channels increases Ca2+ influx, cell migration, and, presumably, tumor cell invasion." (PMID 35982414, 2022). "Upon activation of TRPA1 in cancer cells, increases in Ca2+ influx modulates cell migration and, presumably, tumor invasion." (PMID 35982414, 2022). "It would be also interesting to synthesize and develop pharmacological compounds that target TRPV1, TRPV2, and TRPA1 that were shown to be downregulated in some types of cancers and whose activity enhances differentiation and impairs stemness." (PMID 36142596, 2022). "For example, the expressions of TRPM2, TRPA1, and TRPM8 were associated with patient survival in 22, 16, and 19 cancer types, respectively." (PMID 35614079, 2022). "Diverse mechanisms have been revealed in CAF–cancer Ca2+ signaling; however, TRPA1-mediated VEGF secretion has emerged as a consistent contributor to disease progression." (PMID 34768796, 2021).